G6PD (glucose-6-phosphate dehydrogenase)
Diseases named in the same sentence as G6PD in open-access papers (continued):
Sharing a sentence is not in itself a finding about the gene and the disease.
cancer (continued). "The results demonstrated that the GM+CTCs marked by PGK1 and G6PD were closely associated with the patients’ clinical stage, cancer metastasis and serum tPSA level, although they made up only a small part of the total CTCs." (PMID 29954422, 2018). "As early as in 1965 Beaconsfield realized that cancer mortality seemed to be lower in populations where G6PD-deficiency is common due to endemic occurrence of deficient G6PD-variants." (PMID 27872579, 2016). "The well-known finding that regular use of medications with G6PD-inhibiting properties (e.g. aspirin) goes along with a lower cancer risk when compared with the general population underpins the crucial role of active G6PD in tumor formation and growth." (PMID 27872579, 2016). "Data concerning heterogeneity in G6PD transcripts showed similar percent values of mutated clones in the cancer and healthy tissues of both patients A and B, with about 34% average value." (PMID 20186333, 2010). "Logistic regression analysis was conducted to evaluate whether G6PD activity was independently associated with cancer stage." (PMID 41374996, 2025). "Interestingly, hepatocellular carcinoma cells can undergo cellular senescence due to G6PD suppression, causing intracellular oxidative stress, making cancer cells susceptible to certain chemotherapeutics, such as oxaliplatin." (PMID 40956032, 2025). "Their findings suggest that G. lucidum may affect important metabolic pathways associated with cancer progression by targeting G6PD and BCAT1." (PMID 41462671, 2025). "Studies have revealed that G6PD is aberrantly upregulated in various types of cancer, impacting tumor-associated biological processes such as cell cycle regulation, DNA synthesis, and repair, thereby creating conditions conducive to tumorigenesis and progression." (PMID 40136455, 2025). "PAK4, Erk, and PLK1 cause direct phosphorylation of G6PD and promote cancer growth." (PMID 41244835, 2025). "Among the independent variables, only G6PD activity was significantly associated with cancer stage." (PMID 41374996, 2025). "Conversely, G6PD upregulation has been associated with higher cancer risk." (PMID 38969865, 2024). "Notably, G6PD exhibits abnormal elevation in various cancer types, with its aberrant activation associated with the proliferation and invasion of several malignant tumor types (Yang, Stern & Chiu, 2021)." (PMID 38317842, 2024). "Notably, the overexpression of G6PD is strongly associated with increased resistance to oxidative stress, which can otherwise trigger cancer cell apoptosis." (PMID 39519266, 2024). "G6PD is upregulated in many cancers, and G6PD deficiency is associated with lower cancer risk and mortality for some cancers, suggesting that cancer cells may depend on G6PD for survival or proliferation." (PMID 38997257, 2024). "G6PD activation is a first-line response against oxidative stress in cancer cells, and is thought in association with immune escape, tumor progression, and chemotherapy resistance in many cancers, which is contradicts Ding Lei's findings." (PMID 38586328, 2024). "Additionally, G6PD deficiency can have a beneficial effect on cancer treatment and help reverse chemotherapeutic resistance." (PMID 39726786, 2024). "Another metabolic marker implicated with EMT in cancers is G6PD." (PMID 37174052, 2023). "Thereafter, a G6PD-deficiency-associated cancer study was initiated by Beaconsfield in 1965." (PMID 38139067, 2023). "Moreover, the first three cancers with G6PD expression closely linked to Immune Score were LAML (R =0.51, P <0.001), DLBC (P=0.47, P <0.001), and UVM (R =0.33, P <0.001)." (PMID 37601657, 2023).
cancer (continued). "Therefore, we performed the analysis of G6PD drug resistance based on the GDSC database and identified 252 drugs (403 in total) that were significantly associated with G6PD expression in 970 cancer cell lines." (PMID 37601657, 2023). "Besides, G6PD overexpression is associated with the degree and stage of cancer, including the size of the tumor, depth of invasion, lymph node metastasis, distant metastasis, TNM stage, and survival rate." (PMID 35207558, 2022). "This is associated with the abundance of G6PD in many types of human cancer." (PMID 35628385, 2022). "The enzyme G6PD is linked with a poorer patient diagnosis and is overexpressed in human cancers." (PMID 35991850, 2022). "Hence, the upregulation of G6PD facilitates cancer development and is thus associated with a poor prognosis in many forms of carcinomas." (PMID 34900981, 2021). "However, the association between G6PD overexpression and glutamine consumption in cancer cell proliferation is still incompletely understood." (PMID 34572981, 2021). "However, it is difficult to determine the G6PD deficiency contribution against risk for cancer as the role of G6PD goes beyond GSH and TXN system regeneration." (PMID 33477494, 2021). "Aspirin’s ability to decrease G6PD, potentially contributing to prevention of cancer cell growth, is an interesting finding because there are reports that have documented a direct correlation between G6PD deficiency and decreased cancer incidences." (PMID 33260951, 2020). "Cotargeting the positive regulators of these reciprocal crosstalk mechanisms, such as PI3K, AKT, G6PD and nucleotide synthesis may be an effective treatment for cancers with PTEN loss or PI3K activation." (PMID 32312982, 2020). "Here we investigate whether G6PD inhibition causes autophagy alteration, which can potentiate Lapatinib effect on cancer cells." (PMID 30987650, 2019). "Additionally, G6PD levels have been implicated in different pathologies, for example deficiency in hemolysis and overexpression in cancers." (PMID 29048387, 2017). "Exosomes from both the cell lines contained G6PD, transketolase and transaldolase 1 which are part of the pentose phosphate pathway and may be diagnostic of late stage cancer." (PMID 29262670, 2017). "Moreover, NRF2 was shown to promote cancer cell proliferation by increasing NADPH generation through transcriptional up-regulation of a number of enzyme-encoding genes including G6PD." (PMID 24342878, 2013). "A relationship between lethal diseases such as cancer and G6PD deficiency has also been proposed." (PMID 17637841, 2007). "G6PD could be an anticancer target that is associated with prognosis in a variety of cancers." (PMID 37810967, 2023). "Nonetheless, pentose phosphate pathway function may increase during metastasis (20, 28, –30) and higher G6PD expression is associated with worse outcomes in several cancers (31, –33), raising the question of whether metastasizing cells are particularly dependent upon G6PD." (PMID 35110412, 2022). "However, the regulated mechanisms linked to G6PD are complicated and not fully understood; thus, which mechanism is most important in cancer development is still unknown." (PMID 35207558, 2022).
cancer (continued). "Our insight into the association between elevated G6PD expression and resistance to RNA-directed nucleoside analogues strengthens the ties between this metabolic enzyme and the chemoresistant phenotype in cancer and provides valuable information for future studies." (PMID 22848499, 2012). "Therapeutic strategies targeting disulfidptosis include modulation of metabolic pathways-such as the use of GLUT1 or G6PD inhibitors-to selectively induce this form of cell death in cancer cells." (PMID 41930157, 2026). "Pik1 is another kinase that also phosphorylates the G6PD and enhances the PPP flux by promoting the formation of a G6PD dimer to increase the cancer progression." (PMID 41244835, 2025). "Another study shows that inhibiting G6PD increases the efficacy of cancer treatment with cisplatin as well as paclitaxel." (PMID 40076506, 2025). "As G6PD is a key enzyme in pentose phosphate pathway (PPP) metabolism and can regulate cancer metabolism, we investigated the relationship between G6PD and the PI3K/AKT pathway, which plays an important role in cancer metabolism." (PMID 40685383, 2025). "Polo-like kinase 1 (PLK1) coordinates biosynthesis during cell cycle progression and promotes cancer cell growth by directly increasing G6PD phosphorylation and activating the PPP." (PMID 39859324, 2025). "Univariate logistic regression analysis was performed with age, gender, and G6PD activity as independent variables and cancer stage as dependent variable." (PMID 41374996, 2025). "Although this model has been outlined, the reason for the change of G6PD activity in other human cancers remains elusive." (PMID 39894218, 2025). "This aligns with prior research showing G6PD's overexpression in OS and other cancers, contributing to elevated glycolytic activity and lactate production, thereby promoting lactylation." (PMID 40026531, 2025). "Collectively, these results indicate that FOXO1-stimulated G6PD expression in cancer cells can promote their antioxidative capacity, thus reducing apoptosis, increasing proliferation, and enhancing tumor growth under oxidative stress conditions." (PMID 41124013, 2025). "G6PD is involved in numerous diseases, including viral infections, vascular diseases, seizures, and cancer." (PMID 40685383, 2025). "Stratification by cancer stage revealed a progressive increase in G6PD expression with advancing stages, and nodal metastasis (N1) correlated with higher G6PD levels compared to nonmetastatic cases." (PMID 40116585, 2025). "Previous studies indicate that serum G6PD activity elevates as cancer progresses and suggest the potential utility of G6PD activity as a tumor marker reflecting cancer stage, which aligns with the findings of this study." (PMID 41374996, 2025). "G6PD supports rapid cancer cell proliferation via the pentose phosphate pathway by producing NADPH, ribose-5-phosphate, erythrose-4-phosphate, essential for antioxidant defense, as well as nucleic acid and amino acid biosynthesis." (PMID 41374996, 2025). "To address the potential antioxidant-related resistance to PDT, especially in glycolytic cancers, we targeted glucose-6-phosphate dehydrogenase (G6PD), a rate-limiting enzyme in PPP." (PMID 41291487, 2025). "Glucose 6-phosphate dehydrogenase and 6-phosphogluconate dehydrogenase from the pentose phosphate pathway are crucial for providing the energy and biosynthetic demands of cancer cells through glycolysis and the pentose phosphate pathway." (PMID 40142097, 2025). "In colorectal cancer (CRC), G6PD maintains redox balance and shields cancer cells from oxidative stress, contributing to cancer progression." (PMID 39859324, 2025). "Enzymes from the PPP, like glucose 6-phosphate dehydrogenase (G6PD) and 6-phosphogluconate dehydrogenase (6PGD), are essential for fulfilling the energy and biosynthetic requirements of cancer cells." (PMID 40142097, 2025).
cancer (continued). "It has been reported that the high level of G6PD expression indicates the dismal clinical results of various cancer patients and plays a key role in tumorigenesis and chemical resistance." (PMID 41124013, 2025). "Numerous studies have reported the role of G6PD in cancer progression, metastasis and proliferation in cancer cells." (PMID 41514554, 2025). "The pentose phosphate pathway (PPP), a crucial route in glucose metabolism that is essential for the growth and spread of cancer, includes the key enzyme G6PD." (PMID 40190185, 2025). "PLK1 plays a key role in the biosynthesis of cancer cells by promoting the formation of glucose-6-phosphate dehydrogenase (G6PD) active dimers, interacting with them and directly phosphorylation, thereby activating the pentose phosphate pathway (PPP)." (PMID 40612941, 2025). "In cancer cells, enzymes such as pyruvate kinase muscle isoform M2 (PKM2) and glucose‐6‐phosphate dehydrogenase (G6PD) are upregulated to facilitate the oxidative phase in preventing apoptosis of cancer cells." (PMID 40956032, 2025). "Based on previous research, G6PD serves as a central mediator for cancer cell metabolic reprogramming and ccRCC tumorigenesis." (PMID 39894218, 2025). "This emphasizes that FOXO1 induces the resistance to oxidative stress in cancer cells via transcriptional activation of G6PD." (PMID 41124013, 2025). "Extending beyond the established biological mechanisms of G6PD activity in cancer progression, we quantitatively assessed serum G6PD activity and investigated its feasibility for clinical application." (PMID 41374996, 2025). "Our study revealed abnormally high activity of G6PD in ccRCC, highlighting its significant role in the metabolic reprogramming and tumorigenesis of this cancer type." (PMID 39894218, 2025). "Among the SHRPI components, G6PD, HMMR, and NEIL3 were predominantly expressed in cancer cells, with G6PD showing the highest expression proportion." (PMID 41050691, 2025). "G6PD plays an essential role in cell proliferation, survival, and stress responses, particularly in cancer contexts." (PMID 40307857, 2025). "G6PD is gaining attention as a promising biomarker as its biological mechanisms involved in cancer cell proliferation are progressively being elucidated." (PMID 41374996, 2025). "Ultimately, these data identify reliance on NADPH metabolism and the NRF2/G6PD axis in MPNSTs that represents a critical metabolic vulnerability for future therapeutic targeting in these aggressive cancers." (PMID 40802750, 2025). "Recent studies have reported that cancer cells overexpress G6PD to increase NADPH level, thereby adapting to excess oxidative stress and promoting the synthesis of fatty acids required for rapid cell proliferation." (PMID 41514554, 2025). "Among these, the key genes involved in the central carbon metabolism in the cancer pathway were G6PD and zwf, both encoding glucose-6-phosphate 1-dehydrogenase." (PMID 40572225, 2025). "We compared serum G6PD activity across difference cancer stages, performed ROC curve analysis and assessed its predictive performance." (PMID 41374996, 2025). "In cancer cells, the increased activity of G6PD is driven by the reprogramming of the pentose phosphate pathway." (PMID 39726786, 2024). "In this scenario, G6PD tends to be highly expressed in rapidly proliferating cancer cells, such as liver cancer cells, triple-negative breast cancer cells, and prostate cancer cells." (PMID 38589823, 2024). "All these researches indict that the role of PPP in regulating the malignant biological behavior of cancer cells through G6PD and 6PGD." (PMID 39516455, 2024). "G6PD, the key enzyme of this pathway, is overexpressed in various types of cancers, including bladder, breast, prostate, and stomach cancer, among other types of malignancies." (PMID 38739940, 2024). "The upregulation of G6PD is found in various cancers, and its inhibition has a cytotoxic effect on cancer cells." (PMID 38674143, 2024).
cancer (continued). "Upregulation of glucose-6-phosphate dehydrogenase (G6PD) is commonly observed in cancer cells, enhancing their ability to manage oxidative stress and sustain high rates of proliferation." (PMID 39408832, 2024). "Because the implications of G6PD on cancer incidence, progression, and metastasis have been studied and discussed for more than five decades, many approaches have been tried to limit its activity and thus prevent or reduce tumor progression." (PMID 39796677, 2024). "Upregulated G6PD activity is observed in various cancers, including papillary thyroid carcinoma, colorectal, renal, hepatocellular, breast, and PCa." (PMID 38969865, 2024). "Although cancer cells that overexpress G6PD are vulnerable to ROS accumulation, normal cells are also at risk." (PMID 39796677, 2024). "In cancer cells, the overexpression of G6PD and the subsequent activation of the pentose phosphate pathway are often driven by oncogenic signaling pathways, including the NFE2L2 pathway." (PMID 39534872, 2024). "Preclinical studies have demonstrated that silencing G6PD exerts antiproliferative effects on cancer cell growth." (PMID 39796677, 2024). "First of all, we analyzed the discrepancy of G6PD expression levels between different cancer tissues and normal tissues, and there were significant differences in G6PD in 17 tissues." (PMID 38297250, 2024). "All these data indicate that reduced G6PD has a beneficial effect on cancer incidence and/or progression more broadly." (PMID 38879607, 2024). "Inhibiting the PPP, particularly its rate-limiting enzyme G6PD and its modulators like Nrf2, presents a challenge but holds considerable promise for cancer treatment." (PMID 39796677, 2024). "In cancer, aberrant activation of G6PD and the PPP has been observed, leading to increased NADPH production, fatty acid synthesis, and nucleic acid synthesis—processes that support rapid tumor growth and enhance resistance to oxidative stress." (PMID 39796677, 2024). "Many cancers exhibit upregulated G6PD expression, which enhances their ability to cope with oxidative stress, supports rapid cell growth, and contributes to metabolic reprogramming that favors tumor progression." (PMID 39534872, 2024). "The upregulation of G6PD through NFE2L2 activation not only aids in the detoxification of ROS but also contributes to the resistance of cancer cells to ferroptosis." (PMID 39534872, 2024). "The role of G6PD in cancer development depends on its metabolic function in producing NADPH to reduce ROS and to support reductive biosynthesis." (PMID 38997257, 2024). "The GLUT1/aldolase B/G6PD axis induces chemotherapy resistance and is considered one of the therapeutic targets in cancer." (PMID 39726786, 2024). "In vitro, genetic and pharmacological G6PD inhibition decreased cancer growth and migration, leading to alterations in cellular redox balance and heightened sensitivity to chemotherapy." (PMID 38969865, 2024). "The role of G6PD on cancer progression, its potential as a drug target, and the influence of several factors on G6PD activity is further discussed in this section." (PMID 39796677, 2024). "We found a statistically prominent difference in G6PD expression level between cancer tissues and para-carcinoma tissues of patients with LIHC." (PMID 38297250, 2024). "G6PD inhibitors, such as 6-aminonicotinamide and dehydroepiandrosterone, have been widely used in many cancers." (PMID 39025830, 2024). "G6PD has been proposed as a potential therapeutic target for cancer therapy in recent years due to its overexpression in various cancers." (PMID 38997257, 2024).